SEC16B (SEC16 homolog B, endoplasmic reticulum export factor)
Description:
Plays a role in the organization of the endoplasmic reticulum exit sites (ERES), also known as transitional endoplasmic reticulum (tER). Required for secretory cargo traffic from the endoplasmic reticulum to the Golgi apparatus. Involved in peroxisome biogenesis. Regulates the transport of peroxisomal biogenesis factors PEX3 and PEX16 from the ER to peroxisomes.
Synonyms: RGPR-p117; LZTR2; RGPR; SEC16S; PGPR-p117; CRYZL2P-SEC16B
Tractability: Antibody: UniProt places it where antibodies can reach, with medium confidence; the Human Protein Atlas places it where antibodies can reach. PROTAC: its protein half-life has been measured.
Gene: Protein-coding gene on chromosome 1 (177,923,956 to 177,984,303, reverse strand). Ensembl gene ENSG00000120341.
Subcellular location: Endoplasmic reticulum membrane; Golgi apparatus membrane
Subcellular location (Human Protein Atlas): Endoplasmic reticulum; Plasma membrane; Actin filaments
Pathways (Reactome):
Vesicle-mediated transport: COPII-mediated vesicle transport
Gene Ontology:
Molecular function: protein binding; protein-membrane adaptor activity
Biological process: endoplasmic reticulum organization; endoplasmic reticulum to Golgi vesicle-mediated transport; ER-dependent peroxisome organization; peroxisome fission; positive regulation of gene expression
Cellular component: endoplasmic reticulum exit site; endoplasmic reticulum membrane; cytosol; ER to Golgi transport vesicle membrane; Golgi membrane
Genetic constraint (gnomAD): Loss-of-function variants: 102 observed, 106.71 expected, observed/expected ratio (o/e) 0.96, 90% interval 0.81 to 1.13. The upper end of that interval is the gene's LOEUF score, 1.13, which puts it in group 4 of 6, group 1 being the genes least tolerant of losing a copy. Missense variants: 1,215 observed, 1,175.6 expected, observed/expected ratio (o/e) 1.03, 90% interval 0.99 to 1.08. Synonymous variants: 474 observed, 453.03 expected, observed/expected ratio (o/e) 1.05, 90% interval 0.97 to 1.13.
Homologues: Orthologues: chimpanzee SEC16B (98% identical), macaque SEC16B (94% identical), dog SEC16B (77% identical), pig SEC16B (76% identical), mouse Sec16b (73% identical), rat Sec16b (73% identical), rabbit SEC16B (69% identical), tropical clawed frog sec16b (37% identical), zebrafish sec16b (30% identical), Drosophila melanogaster Sec16 (24% identical), Caenorhabditis elegans sec-16A.2 (19% identical). Paralogues in human: SEC16A (34% identical).
Diseases named in the same sentence as SEC16B in open-access papers:
SEC16B is named in the same sentence as 19 diseases in open-access papers, as found by Europe PMC text mining. Sharing a sentence is not in itself a finding about the gene and the disease. The quoted sentences say what the papers report.
Obesity (34 papers, 2010 to 2025). Accumulation of substantial excess body fat. "This suggests that genetic variants, such as BDNF rs6265, FTO rs1421085, and SEC16B rs506589, are more likely to predispose individuals to obesity when their energy intake is below the EER." (PMID 40002356, 2025). "In the Asian context, a GWAS study from a Japanese sample found two significant obesity-related variants in SEC16B (rs10913469) and GNPDA2 genes." (PMID 40024983, 2025). "Nevertheless, variants of the SEC16B gene have consistently been shown to be linked to human obesity, especially in Asian populations." (PMID 36839421, 2023). "SEC16B has been indicated to be strongly associated with obesity in multiple studies with different populations." (PMID 36676030, 2022). "The genetic polymorphisms of the SEC16B gene region showed significant associations with obesity; SEC16B is a well-known obesity-related genetic variant." (PMID 36233190, 2022). "TMEM18 and SEC16B were associated with an increased risk of obesity of 27% and 40%, respectively, in Hispanic/Latino children (22–88% frequency)." (PMID 36499740, 2022). "SEC16B is not only an obesity susceptibility locus in individuals of Asian and European ancestry but also is related to BMI in individuals of African ancestry." (PMID 33193685, 2020). "This polymorphism, together with rs10913469 in SEC16B gene, was associated with adult obesity in a Japanese population and Caucasians children." (PMID 31354816, 2019). "A recent study showed that SEC16B plays an important role in chylomicron metabolism, which may shed light on the association between variants in this gene and obesity in humans." (PMID 41082226, 2025). "The SEC16B gene region was also the top significant gene region associated with abdominal obesity (p-value = 3.20 × 10−9), and the trends for the sex and age groups were similar to those for general obesity." (PMID 36233190, 2022). "SEC16B has been associated with obesity-related phenotypes but the mechanism behind remains unknown." (PMID 27788139, 2016). "However, SEC16B is an interesting biological candidate gene for obesity related traits as it encodes the long Sec16L and the short Sec16 proteins, which are required for the vesicular transport of secretory molecules from the endoplasmic reticulum (ER) to the Golgi apparatus." (PMID 30026463, 2018). "Intestine-specific Sec16b knockout mice were recently shown to have impaired chylomicron lipidation and protection from high-fat diet-induced obesity and glucose intolerance." (PMID 39948378, 2025). "In studies conducted in adults, SNPs in the genes FTO, MC4R, TMEM18, TNNI3K, SEC16B, GNPDA2, and POMC are strongly associated with obesity risk." (PMID 40722558, 2025). "Our study, along with this experimental evidence, therefore, supports prioritization of intestinal SEC16B as a therapeutic target for obesity and impaired glucose tolerance." (PMID 37749083, 2023). "For example, SEC16B – a protein expressed mostly in the small intestine that is predicted tractable by antibody therapeutics – links obesity with T2DM and metabolic syndrome." (PMID 37749083, 2023). "The SEC16B gene in mice is required for lipid absorption, and is reported to be closely related to obesity in the human population." (PMID 36185367, 2022). "Another study has shown that SEC16B and TMEM18 were associated with 27% and 40% increased odds of obesity, respectively, in Hispanic/Latino children (22–88% frequency)." (PMID 36499740, 2022). "Variants in MC4R, SEC16B and TMEM18 that associated with coffee consumption in previous GWAS are also GWAS-confirmed obesity loci." (PMID 34903748, 2021). "We identified the nominally significant associations with obesity for effect alleles of 6 SNPs at FTO, SEC16B, TFAP2B, RBJ, MAP2K5 and CDKAL1 (ORs for the effect allele ranged between 1.19 and 1.41, nominal two-sided P < 0.05)." (PMID 26800887, 2016).
Obesity (continued). "SNPs in the FTO, GNPDA2, SEC16B, BDNF, TMEM18 and NPC1 loci associated with increased risk of both overweight and obesity." (PMID 23861046, 2013). "Similarly, on Mexican mestizos, researchers found a link between obesity and various genetic variants like NEGR1, MTCH2, and SEC16B which are also prevalent in other ethnic populations." (PMID 40024983, 2025). "Finally, we examined the effect of mutations in zebrafish orthologues of several genes associated with polygenic forms of obesity that previously showed some evidence of a causal role (i.e., NEGR1, SEC16B, ARID5B, IRS1, and IRS2)." (PMID 39948378, 2025). "So far, however, the physiological role of SEC16B in obesity or related metabolic diseases remains unknown." (PMID 36676030, 2022). "It has been reported that obesity may be triggered by the expression of SEC16B, which affects the synthesis and transport of lipase, then inhibiting the decomposition of fat." (PMID 35295960, 2022). "SEC16B has been identified in multiple obesity GWASs but its physiological role in energy homeostasis remains unknown." (PMID 36676030, 2022). "The findings from the present study provide no consistent statistically significant evidence for an association of the five investigated obesity-associated genes (FTO, TMEM18, MC4R, SEC16B, and BDNF) with baseline anthropometric traits or their changes after 12 months of behavioural intervention." (PMID 33801339, 2021). "SEC16B-rs574367 could affect the synthesis and transcription of lipase, thus inhibiting the decomposition of fat, leading to the occurrence of obesity." (PMID 32260174, 2020). "Our study has replicated known body composition loci including SEC16B, FTO and NEGR1 and resulted in the discovery of new signals that may associate with an increased risk for obesity-related traits." (PMID 30026463, 2018). "The results demonstrated that genetic variation in KCNJ11, BDNF, PFKP, PTER and SEC16B were associated with SGA and support the concept that genetic factors associated with obesity and/or type 2 diabetes are more prevalent in those born SGA compared to those born AGA." (PMID 20712903, 2010). "Obesity and adiposity are influenced by genes like ADCY3, NPY2R, and SEC16B, which play central roles in MetS pathophysiology." (PMID 39858569, 2024). "Thus, we demonstrate that the currently known major common variants related to obesity overlap to a substantial degree between children and adults confirming previous observations for FTO, MC4R, TMEM18, NEGR1 and extending this observation to SEC16B, BDNF and BCDIN3D;." (PMID 20421936, 2010). "dSec16 is a Drosophila homolog of human SEC16B, which was identified as an obesity gene in multiple GWASs but was not functionally validated." (PMID 36676030, 2022). "Leaving the hypothesis-free approach and focussing on known GWAS-based candidate markers, we were able to substantiate another four loci (NEGR1, SEC16B, BDNF and BCDIN3D) of the 16 obesity loci previously detected in GWAS." (PMID 20421936, 2010). "Among the available phenotypes, obesity was chosen because it has been subjected to a number of high quality and well-powered GWAS that have identified more than 100 loci, many that have been consistently replicated across studies (e.g. FTO, BDNF, MC4R, TMEM18, SEC16B)." (PMID 33947323, 2021).
central obesity (3 papers, 2021 to 2022). "A higher socioeconomic status aggravated the influence of SNPs (including FTO rs9939609, BNDF rs11030104, etc.)on BMI and WC, and aggravated the influence of SEC16B rs574367 on central obesity." (PMID 33668547, 2021).
atherosclerosis (2 papers, 2026). A disease characterized by the build-up of fatty material and calcium deposition in the arterial wall resulting in partial or complete occlusion of the arterial lumen. "Hepatic deletion of SEC16B in mice markedly reduces circulating APOB, triglycerides and cholesterol, while conferring robust protection against atherosclerosis and cardiac dysfunction and maintaining liver health." (PMID 42032080, 2026).
Insulin resistance (1 paper, 2020). Increased resistance towards insulin, that is, diminished effectiveness of insulin in reducing blood glucose levels. "Three SNPs were associated with increased insulin resistance risk with adjusting for covariates, including 5q11.2-rs4432842 (OR = 1.23, 95% CI: 1.04–1.45), RASGRP1-rs7403531 (OR = 1.35, 95% CI: 1.13–1.62), SEC16B-rs574367 (OR = 1.34, 95% CI: 1.07–1.67)." (PMID 32260174, 2020).
male infertility (1 paper, 2022). The inability of the male to effect fertilization of an ovum after a specified period of unprotected intercourse. "In cattle, variants in SEC16B, VGLL3, and DEBB119 were also associated with male infertility." (PMID 36140773, 2022).
osteogenesis imperfecta (1 paper, 2023). Osteogenesis imperfecta (OI) comprises a heterogeneous group of genetic disorders characterized by increased bone fragility, low bone mass, and susceptibility to bone fractures with variable severity. "In our current work, we provide evidence that SEC16B regulates trafficking from the ER and that its loss of function results in osteogenesis imperfecta." (PMID 36916446, 2023).
cancer (2 papers, 2021 to 2022). A tumor composed of atypical neoplastic, often pleomorphic cells that invade other tissues. "Interestingly, high mRNA expression levels of RAB31 and SEC16B predicted cancer cell lines resistant to 62 and 17 small molecule anticancer drugs, respectively." (PMID 34359748, 2021). "In addition, our results suggested an association between high mRNA expression levels of RAB31 and SEC16B and the resistance of various cancer cell lines to 62 and 17 of small molecule anti-cancer drugs, respectively." (PMID 34359748, 2021). "Notably, RAB31, IRAK3, OBSCN, LIN9, TNPO2, and SEC16B expressions were inversely correlated with the gene expression profiles suggestive of tumor purity of the hub cancer." (PMID 34359748, 2021). "However, the negative association between the levels of LIN9 and SEC16B and the gene expression profile suggestive of CAFs infiltrations of the hub cancers suggested that the hub genes are likely to be involved in the regulation of tumor immune evasion via different mechanisms." (PMID 34359748, 2021). "Specifically, single nucleotide variation (SNV) of OBSCN is the most frequently predicted gene alteration, while SNV of SEC16B, IRAK3, TNPO2, LIN9, and RAB31 constituted 9%, 5%, 5%, 4%, and 2% of genetic alterations in the TCGA cohort of the hub cancers." (PMID 34359748, 2021). "Similarly, the expression levels of RAB31, IRAK3, and SEC16B were inversely correlated, while TNPO2 and LIN9 were positively correlated with gene expression profiles suggestive of MDSCs infiltration in the six cancer types." (PMID 34359748, 2021). "Similarly, we queried the survival differences between the mRNA expression levels of each hub gene across the combined cohorts of the hub cancers and found that higher mRNA expression levels of RAB31, IRAK3, SEC16B, and LIN9 predicted shorter survival durations of the hub cancer cohorts." (PMID 34359748, 2021).
tumor (1 paper, 2021). "The prioritization of the hub genes in the gene expression profiles suggestive of tumor immune evasion and immunotherapy response occurs in the order of RAB31 > TNPO2 > OBSCN > IRAK3 > LIN9 > SEC16B." (PMID 34359748, 2021).
SEC16B also shares sentences with these, for which no sentence is quoted: type 2 diabetes (2 papers); breast carcinoma (1); cardiovascular disease (1); ciliopathy (1); colorectal cancer (1); diabetes (1); Impaired glucose tolerance (1); lung carcinoma (1); metabolic syndrome (1); prostate carcinoma (1); Stomach Cancers (1).